PFKFB3 (6-phosphofructo-2-kinase/fructose-2,6-biphosphatase 3)
Diseases named in the same sentence as PFKFB3 in open-access papers (continued):
Sharing a sentence is not in itself a finding about the gene and the disease.
cognitive decline (1 paper, 2024). "Furthermore, these mice displayed cognitive decline and a metabolic syndrome that was mimicked by confining Pfkfb3 expression to hypothalamic neurons." (PMID 38789798, 2024).
corneal infection (1 paper, 2025). A viral or bacterial infectious process affecting the cornea. "The severity of corneal infection following PFKFB3 depletion was checked by slit-lamp microscopy, corneal OCT, and H&E staining." (PMID 41425966, 2025). "Whereas inflammation in BMDM and the degree of fungal keratitis lesions worsen by suppressing PFKFB3 expression, which increased corneal ulcer infiltration, elevated clinical scores, enhanced corneal thickness, and upregulation of inflammatory signals could be demonstrated." (PMID 41425966, 2025).
coronary atherosclerosis (1 paper, 2020). Atherosclerosis of the coronary vasculature. "In patients with severe symptomatic coronary atherosclerosis, monocytes display a distinct glycolytic phenotype by overexpressing hexokinase 2 and PFKFB3." (PMID 33282864, 2020).
cutaneous squamous cell carcinoma (1 paper, 2021). "Taken together, KLF9-induced PFKFB3 downregulation inhibits the proliferation, metastasis and aerobic glycolysis of cutaneous squamous cell carcinoma cells." (PMID 34612136, 2021). "In conclusion, PFKFB3 was transcriptionally regulated by KLF9, and PFKFB3 silencing inhibits the proliferation, metastasis, and aerobic glycolysis of cutaneous squamous cell carcinoma cells." (PMID 34612136, 2021). "However, the role of PFKFB3 in cutaneous squamous cell carcinoma has not been reported." (PMID 34612136, 2021).
diffuse midline glioma (1 paper, 2024). A diffuse glioma that arises from the midline structures of the central nervous system. "A recent study demonstrated that in diffuse midline glioma, ERK5 regulates the proglycolytic isoenzyme 6-phosphofructo-2-kinase/fructose-2,6-biphosphatase 3 (PFKFB3) via the activation of transcriptional factor MEF2A." (PMID 38542254, 2024).
Duchenne muscular dystrophy (1 paper, 2024). Duchenne muscular dystrophy (DMD) is a neuromuscular disease characterized by rapidly progressive muscle weakness and wasting due to degeneration of skeletal, smooth and cardiac muscle. "It further added that a fusion transcript was detected, PFKFB3::DMD, with reads spanning exon 1 of PFKFB3 to exon 45 of DMD, providing even more conclusive evidence that the 306 kb inverted insertion of 10p15.1 is the pathogenic variant that results in Duchenne muscular dystrophy in both boys." (PMID 39595988, 2024).
epilepsy (1 paper, 2021). A brain disorder characterized by episodes of abnormally increased neuronal discharge resulting in transient episodes of sensory or motor neurological dysfunction, or psychic dysfunction. "Overall, miR-485 inhibited apoptosis, oxidative stress, and inflammation in epilepsy model cells through the HDAC5/HIF1α/PFKFB3 axis." (PMID 34021541, 2021). "Given the involvement of PFKFB3 is involved in neuronal excitotoxicity, which is an important mechanism for epilepsy, we set about to investigate the interactions among miR-485, with HDAC5, HIF1α, and PFKFB3 in cellular and animal models of epilepsy." (PMID 34021541, 2021). "Adding to this base, we now present strong evidence that PFKFB3 regulation is also involved in epilepsy." (PMID 34021541, 2021). "Previous works show that PFKFB3 is involved in neuronal excitotoxicity, which is an important mechanism for epilepsy." (PMID 34021541, 2021). "The forced HDAC5 overexpression increased HDAC5, HIF1α, and PFKFB3 expression in the presence of miR-485 mimic in epilepsy model cells, but increased HIF1α and PFKFB3 expressions only in the presence of miR-485 mimic." (PMID 34021541, 2021). "Taken together, these results show that miR-485 inhibited epilepsy through the HDAC5/HIF1α/PFKFB3 axis in vivo." (PMID 34021541, 2021). "HDAC5 silencing reduced apoptosis in epilepsy model cells, which was reversed by HIF1α or PFKFB3 overexpression." (PMID 34021541, 2021). "miR-485 mimic reduced HDAC5, HIF1α, and PFKFB3 expressions in epilepsy model cells." (PMID 34021541, 2021). "In conclusion, miR-485 alleviates epilepsy through inhibition of HDAC5, leading to downregulation of HIF1α and PFKFB3." (PMID 34021541, 2021). "Collectively, we find that miR-485 alleviates epilepsy by inhibiting HDAC5, HIF1α, and PFKFB3 expression, thus presenting therapeutic targets for the treatment of epilepsy." (PMID 34021541, 2021). "Thus, miR-485 alleviates neuronal damage and epilepsy by inhibiting HDAC5, HIF1α, and PFKFB3." (PMID 34021541, 2021).
fungal keratitis (1 paper, 2025). "We identified the up-regulation of PFKFB3 in fungal keratitis via western blot, quantitative real-time polymerase chain reaction (RT-PCR), and immunofluorescence staining." (PMID 41425966, 2025). "After infection, moderate PFKFB3 activation effectively mitigates inflammation and the progression of fungal keratitis." (PMID 41425966, 2025). "However, the involvement of PFKFB3 in macrophages in the pathogenesis of fungal keratitis remains ambiguous, with limited knowledge of its role in this condition; thus, the mechanisms associated with PFKFB3 in fungal keratitis require urgent investigation." (PMID 41425966, 2025). "We conclude that targeting macrophage PFKFB3 in fungal keratitis may be a unique therapeutic approach for addressing this illness." (PMID 41425966, 2025). "Our results speculated that the PI3K/AKT/NF-κB p65 signaling pathway contributes to the protective function of PFKFB3 on fungal keratitis." (PMID 41425966, 2025). "Overall, our study signifies that PFKFB3 may be a promising target for treating fungal keratitis." (PMID 41425966, 2025).
glucose metabolism (1 paper, 2025). "Overall, the results of this study indicate that EVs-delivered PFKFB3 small molecule inhibitor quercetin can not only inhibit the inflammatory response in AP but also potentially improve glucose metabolism disorders by regulating glycolysis-related pathways and inhibiting oxidative stress." (PMID 40618046, 2025).
Glucose Metabolism Disorder (1 paper, 2025). "Collectively, this study demonstrates that PFKFB3 small molecule inhibitors loaded in cell membrane nanovesicles can effectively improve glucose metabolism disorder and inflammatory response in an AP rat model." (PMID 40618046, 2025). "Accordingly, regulating PFKFB3, particularly through small molecule inhibitors, offers a promising strategy for improving glucose metabolism disorders in AP." (PMID 40618046, 2025). "This study reveals the critical role of PFKFB3 in glucose metabolism disorder following AP and is the first to apply cell membrane nanovesicle technology to deliver the PFKFB3 small molecule inhibitor quercetin." (PMID 40618046, 2025). "Given the critical role of glucose metabolism disorders in AP, we focused on PFKFB3, a key glycolytic regulatory enzyme whose activity is closely linked to various metabolic and inflammatory diseases." (PMID 40618046, 2025). "This study explores the role of PFKFB3 in glucose metabolism disorder following AP through bioinformatics analysis and experimental validation, providing new perspectives and strategies for AP treatment." (PMID 40618046, 2025).
gouty arthritis (1 paper, 2020). "In our experiment, besides the increased expression of the key enzymes related to glycolysis (GLUT1, PFK1, PFKFB3, and LDH), the concentration of lactic acid was also enhanced in both feces and serum, indicating an increase in glycolysis in the mice model with gouty arthritis." (PMID 33603667, 2020).
gynecological cancers (1 paper, 2021). "PFK158, another novel PFKFB3 inhibitor, was proven effective in gynecological cancers and mesothelioma." (PMID 33671514, 2021). "As standard chemotherapy inevitably leads to the development of chemoresistance, the observation that PFKFB3 inhibition therapy synergizes with carboplatin and paclitaxel in resistant cell lines of gynecological cancers to reduce tumor weight presents an intriguing therapeutic avenue." (PMID 33671514, 2021).
hemangioma (1 paper, 2023). A benign vascular lesion characterized by the formation of capillary-sized or cavernous vascular channels. "PFKFB3 was identified as one of the most significant DEGs and was more highly expressed in proliferating IH tissues and hemangioma-derived endothelial cells (HemECs) than in involuting IH tissues and human umbilical vein endothelial cells, respectively." (PMID 36740704, 2023).
Huntington disease (1 paper, 2025). Huntington disease (HD) is a rare neurodegenerative disorder of the central nervous system characterized by unwanted choreatic movements, behavioral and psychiatric disturbances and dementia. "Furthermore, ARRB2 and PFKFB3 are promising biomarker candidates for Huntington’s disease (HD) due to their involvement in key pathological processes—ARRB2 in neuronal signaling and cell death, and PFKFB3 in glycolytic metabolism and energy stress." (PMID 40643497, 2025).
Hypoglycemia (1 paper, 2020). A decreased concentration of glucose in the blood. "Reduced expression of key gluconeogenic genes including Pck1, G6Pc, and Pfkfb3 in L-GRKO mice is linked to fasting hypoglycemia, and around half of newborn albumin-alpha-fetoprotein-driven L-GRKO mice die within 48 h after birth, possibly due to hypoglycemia." (PMID 33133019, 2020).
idiopathic pulmonary fibrosis (1 paper, 2022). Idiopathic pulmonary fibrosis (IPF) is a nonneoplastic pulmonary disease that is characterized by the formation of scar tissue within the lungs in the absence of any known cause. "In the lung tissue of patients with idiopathic pulmonary fibrosis (IPF), disruption of amino acid metabolism and glycolysis has been evidenced and glycolytic enzymes (including PFKFB3, PFK1, and HK2) are upregulated." (PMID 36121543, 2022).
infarction (1 paper, 2023). A localised pathological necrosis of tissue resulting from obstruction of the blood supply usually by a thrombus, an embolus, or vascular torsion. "PFKFB3 expression levels increased on day 3 after MI and then declined in the late post-infarction period, and continuous inhibition of its function by 3PO significantly led to improved cardiac function and fibrotic remodeling on day 28 after MI." (PMID 37509108, 2023).
ischemia reperfusion injury (1 paper, 2025). Adverse functional, metabolic, or structural changes in ischemic tissues resulting from the restoration of blood flow to the tissue (reperfusion), including swelling; hemorrhage; necrosis; and damage from free radicals. "In ischemia–reperfusion injury (IRI) mice, the elevated levels of the glycolytic enzyme 6-phosphofructo-2-kinase/fructose-2,6-biphosphatase 3 (PFKFB3) mediate increased H4 K12 lactylation." (PMID 40478495, 2025).
keratitis (1 paper, 2025). A corneal disease that is characterized by inflammation of the cornea. "However, future research needs to examine the pivotal role of PFKFB3 overexpression in inflammation and keratitis consequences." (PMID 41425966, 2025).
liver cirrhosis (1 paper, 2025). "In the present investigation, PFKFB3 levels were markedly increased in the kidney of LC rats with alcohol-acetaminophen-induced liver cirrhosis." (PMID 40271532, 2025).
Lyme borreliosis (1 paper, 2021). "Indeed, increased PFKFB3, HK2, and LDHA gene expression has been observed in Lyme borreliosis patients, as well as increased levels of serum lactate." (PMID 33395408, 2021).
lysosomal storage disease (1 paper, 2022). A metabolic disorder caused by mutations in proteins critical for lysosomal function, including lysosomal enzymes, lysosomal integral membrane proteins, and proteins involved in the post-translational modification and trafficking of lysosomal proteins. "Thus, aberrant upregulation of the glycolytic enzyme PFKFB3 in neurons may contribute to CLN7 pathogenesis and targeting PFKFB3 could alleviate this and other lysosomal storage diseases." (PMID 35087090, 2022).
metabolic syndrome (1 paper, 2024). A cluster of metabolic risk factors for CARDIOVASCULAR DISEASES and TYPE 2 DIABETES MELLITUS. "Thus, neurons are metabolically inflexible cells unable to adapt to the sustained active glycolysis that is linked with neurological and metabolic syndromes, in which neuron-specific inhibition of PFKFB3 may be considered as a therapeutic opportunity." (PMID 38789798, 2024).
myeloproliferative neoplasm (1 paper, 2022). A clonal hematopoietic stem cell disorder, characterized by proliferation in the bone marrow of one or more of the myeloid (i.e., granulocytic, erythroid, megakaryocytic, and mast cell) lineages. "Blockade of PFKFB3 by 3PO in mutant JAK2-driven myeloproliferative neoplasms alters redox homeostasis through inhibiting glycolysis, thus, resulting in accumulation of reactive oxygen species and increased apoptosis." (PMID 35155224, 2022).
Myocardial fibrosis (1 paper, 2025). "Additionally, myocardial fibrosis markers were significantly reduced, accompanied by a decrease in the myocardial mRNA and protein expression of glycolytic proteins, including HIF-1α, PFKFB3, GLUT1, and LDHA." (PMID 40944191, 2025).
osteonecrosis (1 paper, 2024). A none disease characterized by death of bone tissue due to a lack of blood supply. "The increased sympathetic tone stimulates endothelial glycolysis via the Adrb2/CREB/PFKFB3 signals and promotes H-type vessel angiogenesis coupled with osteogenesis, thereby delaying and protecting against GC-induced osteonecrosis." (PMID 39516484, 2024). "Endothelial-specific overexpression of PFKFB3 attenuates endothelial impairment and prevents severe osteonecrosis in MPS-treated Adrb2 knockout mice." (PMID 39516484, 2024). "Finally, overexpression of PFKFB3 rescued GC-induced osteonecrosis in an Adrb2 knockout mice." (PMID 39516484, 2024).
osteoporosis (1 paper, 2021). A condition of reduced bone mass, with decreased cortical thickness and a decrease in the number and size of the trabeculae of cancellous bone (but normal chemical composition), resulting in increased fracture incidence. "Our study adds to the evidence that Pfkfb3 may influence bone metabolism in the context of microgravity, disuse-induced bone loss and osteoporosis." (PMID 34637435, 2021). "Pfkfb3 was also identified de-novo in a gene enrichment analysis of circulating monocytes in patients with osteoporosis, further suggesting a possible role in modulating the bone microenvironment in the setting of low bone density." (PMID 34637435, 2021).
Peritoneal Fibrosis (1 paper, 2023). Disorder characterized by a wide range of structural changes in PERITONEUM, resulting from fibrogenic or inflammatory processes. "The functional importance of this hyperglycolysis is shown by endothelial PFKFB3 deficiency, which not only decreases glycolysis, but also lessens peritoneal fibrosis and dysfunction." (PMID 38037461, 2023).
prostate tumors (1 paper, 2025). "Moreover, PFKFB3 is frequently overexpressed in lung, breast, and prostate tumors." (PMID 41296396, 2025).
rectal adenocarcinoma (1 paper, 2021). "In this study we individually evaluated PFKFB3 expression in normal colon and rectal mucosa and compared it to colon and rectal adenocarcinoma, and correlated its levels with survival rates." (PMID 33671096, 2021). "Therefore, we decided to individually evaluate PFKFB3 gene expression in normal colon and rectal mucosa in comparison to colon and rectal adenocarcinoma." (PMID 33671096, 2021).
respiratory failure (1 paper, 2025). The significant impairment of gas exchange within the lungs resulting in hypoxia, hypercarbia, or both, to the extent that organ tissue perfusion is severely compromised. "Findings indicate that PFKFB3 is a molecular switch that regulates the use of glucose vs. fructose in glycolysis, thereby enhancing our understanding of lung endothelial cell metabolism during respiratory failure." (PMID 40547131, 2025).
skin cutaneous melanoma (1 paper, 2023). "Our results show that PFKFB3 expression was correlated positively with TMB in THYM, ACC, COAD, SARC, and skin cutaneous melanoma (SKCM); and correlated negatively with TMB in LUSC, BRCA, brain lower grade glioma (LGG), THCA, PRAD, LIHC, and UVM." (PMID 37253634, 2023).
tongue tumor (1 paper, 2017). "And of interest, a recent study showed PFKFB3 controled human tongue tumor growth by responding to the circadian clock outputs." (PMID 28061878, 2017).
ulcerative colitis (1 paper, 2026). An inflammatory bowel disease involving the mucosal surface of the large intestine and rectum. "But the functional relevance and mechanistic basis of the PFKFB3 on ulcerative colitis (UC) remain unclear." (PMID 41378888, 2026).